ENSG00000252143
Synonyms: LOC124905173
Gene: Small Cajal body-specific RNA gene on chromosome 22 (21,544,897 to 21,545,039, forward strand). Ensembl gene ENSG00000252143.
Gene Ontology:
Biological process: RNA processing
Cellular component: Cajal body; nucleolus